LRP1 (LDL receptor related protein 1)
Diseases named in the same sentence as LRP1 in open-access papers (continued):
Sharing a sentence is not in itself a finding about the gene and the disease.
Cognitive impairment (24 papers, 2014 to 2026). Abnormal cognition is characterized by deficits in thinking, reasoning, or remembering. "This study aimed to investigate the pathogenetic roles of LRP1 and its rs1799986 polymorphism in mild cognitive impairment (MCI) among patients with type 2 diabetes mellitus (T2DM)." (PMID 33013281, 2020). "Furthermore, with the prevalence of long COVID and persistent cognitive impairment associated with COVID-19, it is important to note that both LRP1 and LRP2 have been shown to endocytose ligands across the blood–brain barrier." (PMID 40349772, 2025). "In the ROSMAP brain transcriptomics dataset, the expression of these genes (except for LRP1) was selectively reduced in female patients and correlated with cognitive impairment." (PMID 41274899, 2025). "Reduction in hepatic LRP-1 regulated by PPARα contributes to impaired peripheral Aβ clearance, thereby leading to cerebral Aβ accumulation and cognitive impairment in NAFLD." (PMID 38507874, 2024). "Conversely, overexpression induced by transfection LRP-1 in a liver reduced Aβ deposition and cognitive impairments in APP/PS1 mice." (PMID 39456746, 2024). "Taken together, our results underscore the potential mechanism of NAFLD in promoting cognitive impairment by impeding LRP-1-mediated peripheral Aβ clearance via the liver." (PMID 38507874, 2024). "Raptorfl/+ diabetic mice had significantly inhibited activation of mTORC1 and SREBP1, increased LRP1 expression, increased Aβ efflux, and improved cognitive impairment." (PMID 36890627, 2023). "In conclusion, our experiments demonstrate that EE is effective in ameliorating the adverse effects of chronic SD on cognitive impairment and Aβ deposition, through coordinating the expression of Aβ transport-related proteins LRP1 and RAGE across the BBB." (PMID 37692085, 2023). "Herein, we elucidated the mechanism by which inhibiting mTORC1 in the brain microvascular endothelium ameliorates diabetic Aβ brain deposition and cognitive impairment via the SREBP1/LRP1 signaling pathway." (PMID 36890627, 2023). "A recent study using a mice diabetes model found that hyperglycemia can impair Aβ efflux in the brain microvasculature by downregulating the expression of LRP1 and resulting in cognitive impairment." (PMID 36964401, 2023). "The results first confirm that Mammalian target of rapamycin complex 1 in the brain microvascular endothelial ameliorates diabetic Aβ brain deposition and cognitive impairment via SREBP1/LRP1 signal pathway." (PMID 36890627, 2023). "In summary, our results have confirmed that inhibiting mTORC1 in the brain microvascular endothelium ameliorates diabetic Aβ brain deposition and cognitive impairment via the SREBP1/LRP1 signaling pathway." (PMID 36890627, 2023). "Studies have confirmed that physical exercise reduces amyloid plaque load in the brain through differential modulation of RAGE and LRP1, thereby ameliorating several pathological mechanisms of AD, such as neurovascular unit dysfunction or cognitive deficits." (PMID 37692085, 2023). "Some studies found that repression of LRP1 leads to Aβ accumulation, eventually ameliorating cognitive deficits in mice, which supports the finding that LRP1 participates in the efflux of Aβ." (PMID 34349624, 2021). "Further studies are warranted to determine the role of LRP1 in mediating cognitive impairment in diabetes." (PMID 33013281, 2020). "Brain endothelial cell-specific LRP1 deletion in AD transgenic mice led to elevated levels of soluble brain Aβ and amyloid plaques, resulting in aggravated cognitive deficits." (PMID 28228716, 2017). "Experimental models have shown that restoring Lrp1 function improves Aβ clearance and mitigates cognitive deficits, suggesting that Lrp1 could be a potential therapeutic target for preventing or treating neurodegenerative diseases in aging populations [1401]." (PMID 40407975, 2025).
Cognitive impairment (continued). "A recent study showed that deletion of brain endothelial LRP1 leads to loss of BBB integrity, neuronal loss, and cognitive deficits in Lrp1lox/lox mice (an endothelial-specific Lrp1 knockout mouse) and that these deficits can be reversed by endothelial-specific LRP1 gene therapy." (PMID 38020775, 2023). "As an important agent of Aβ protein clearance through the blood–brain barrier, low-density lipoprotein receptor-related protein 1(LRP1) may be used as a therapeutic target for regulating the pathological changes of cognitive disorders." (PMID 35800979, 2022). "On the other hand, increasing the LRP1 expression in the hepatocytes of APPswe/PSEN1dE9 mice had an opposite effect—it decreased the amount of Aβ and hyperphosphorylated τ in the brain, reduced neurodegeneration and neuroinflammation and improved cognitive deficits." (PMID 39065645, 2024). "Inhibiting mTORC1 in the brain microvascular endothelium ameliorates diabetic Aβ brain deposition and cognitive impairment via the SREBP1/LRP1 signaling pathway, suggesting that mTORC1 may be a potential target for the treatment of diabetic cognitive impairment." (PMID 36890627, 2023). "Furthermore, Lrp1 gene deletion in forebrain neurons in adult mice by αCaMKII-Cre led to compromised brain lipid metabolism and progressive, age-dependent synaptic dysfunction, cognitive impairments, and eventual neurodegeneration." (PMID 25500815, 2014). "In diabetes, high glucose environments and experimental diabetic models reduce LRP1 expression and function at the BBB, lowering Aβ clearance and worsening cognitive impairment." (PMID 41582996, 2025). "Our findings suggest that LRP-1 mediates the adverse effect of NAFLD on peripheral Aβ clearance, thereby contributing to cerebral Aβ accumulation and cognitive impairment in NAFLD." (PMID 38507874, 2024). "LRP-1 mediates the adverse effect of NAFLD on peripheral Aβ clearance, thereby contributing to cerebral Aβ accumulation and cognitive impairment in NAFLD." (PMID 38507874, 2024). "Second, we found that NAFLD hindered the hepatic uptake of Aβ via the PPARα/LRP-1 pathway, but studies in hepatocyte-specific LRP-1 or PPARα overexpression animal models challenged with a long-term HFD are required to clarify its role in NAFLD-induced Aβ pathology and cognitive impairment." (PMID 38507874, 2024). "The results showed that EE could effectively ameliorate the effects of SD on cognitive impairment, reduce SD induced Aβ deposition, and decrease the expression of RAGE, while increase the expression of LRP1." (PMID 37692085, 2023). "Based on mRNA expression results, RAGE antagonist FPS-ZM1 and LRP1 antagonist RAP, were applied to determine whether JWKXS improved cognitive deficits by regulating Aβ transportation via RAGE and LRP1." (PMID 30941041, 2019). "Tanshinone IIA (Tan IIA) enhances LRP1 expression in both animal models and cultured cells, promoting Aβ transport by alleviating SIRT1-mediated endoplasmic reticulum (ER) stress in brain microvascular endothelial cells (BMECs) to improve cognitive deficits in APP/PS1 mice." (PMID 41582996, 2025).
amyloid (23 papers, 2010 to 2025). "LDC alcohol feeding to Tg2576 mice caused mild liver injury, and important amyloidosis-relevant hepatic proteins (LRP-1 and APP) were largely unaltered." (PMID 40196176, 2025). "In particular, LRP1 mediates Aβ uptake in astrocytes and neurons followed by subsequent lysosomal degradation while mice with LRP1 deficient neurons developed exacerbated amyloid pathology) 56,57." (PMID 37554284, 2023). "Once we established the association of LRP1/syndapin-2 and Aβ, we assessed the levels of syndapin-2 in an amyloidosis mouse model (APP-PS1)." (PMID 35233527, 2022). "LRP1 is also responsible for the endocytosis and degradation of Aβ, or Aβ-ApoE complex, whereby amyloid pathology is enhanced by the APOE4 allele, dependent upon LRP1 uptake." (PMID 34503576, 2021). "The impaired Aβ clearance caused by the astrocytic LRP1 knockdown led to an accelerated amyloid plaque deposition." (PMID 33519378, 2020). "Taken together, our in vitro and in vivo results suggest that another potential mechanism by which STAT3 inhibition attenuates amyloid pathogenesis and its associated neurovascular deficits is by reducing Aβ-induced oxidative stress production and its pathologic impact on LRP-1 expression." (PMID 34911575, 2021). "Low-density lipoprotein receptor-related protein 1 (LRP1) has recently been suggested to be a common factor contributing to the co-occurrence of amyloid and tau pathologies." (PMID 38951140, 2024). "Lower expression of LRP1 in capillary endothelial cells and neurons in the brain of AD patients leads to reduced clearance of Aβ, resulting in amyloid accumulation." (PMID 35209007, 2022). "In fact, APOE ε4-mediated Aβ pathology likely depends on LRP1, as LRP1 deficiency in neurons blocks the APOE ε4-mediated exacerbation of amyloid plaque burden in APP/PS1 (PSEN1) double-transgenic mice." (PMID 32859588, 2020). "The conditional knockout of LRP1 in the neurons of APP/PS1 mice resulted in exacerbated amyloid pathology in the brain." (PMID 28228716, 2017). "Pharmacological approaches to increase circulating soluble LRP1 also appears to ameliorate amyloid pathology in amyloid model mice." (PMID 24904407, 2014). "Conditional deletion of Lrp1 gene in vascular smooth muscle cells in amyloid model APP/PS1 mice accelerated brain Aβ accumulation and exacerbated Aβ deposition as amyloid plaques and CAA, without affecting Aβ production." (PMID 23908553, 2014). "Shifting LRP1 transport towards transcytosis, increasing its levels, and enhancing LRP1-dependent Aβ efflux from the brain significantly reduces amyloid load and restores cognitive function in animals, with the therapeutic effect persisting for an extended period." (PMID 41373742, 2025). "Moreover, we also reveal the relationship between autophagy, cerebral blood flow, ACHE, expression of LRP1, and amyloidosis." (PMID 35209007, 2022). "The authors concluded that the expression of LRP1 and its function in astrocytes could be an effective strategy to counter the amyloid plaque accumulation in AD." (PMID 33519378, 2020). "For example, LRP1 regulates cellular Aβ uptake in neurons and vascular smooth muscle cells, and the disturbances of this pathway exacerbates amyloid pathology in amyloid mouse models." (PMID 27151330, 2016). "This study used genetic tools to reduce LRP1 levels in the brains of mice that co-express APPswe/PS1dE9 and develop amyloid pathology, producing a model in which LRP1 levels in most hippocampal neurons were lowered to below the level of detection by immunohistochemistry." (PMID 22537779, 2012). "Moreover, activating the σ1 receptor increases vascular endothelial growth factor (VEGF) and low-density lipoprotein receptor-related protein 1 (LRP-1) expression levels and attenuates the blood–brain barrier (BBB) dysfunction caused by amyloid deposition in AD." (PMID 37569401, 2023).
amyloid (continued). "To explore additional mechanisms by which STAT3 inhibition positively impacts amyloid deposition, we further examined whether LLL-12 treatment reduces amyloid-induced oxidative stress and its impact on LRP-1—a key molecule involved with Aβ clearance across the blood–brain barrier (BBB)." (PMID 34911575, 2021). "Thus, this genetic test does not produce supportive evidence for the notion that modulating LRP1 function in neurons or glial could be beneficial in modulating amyloidosis." (PMID 22537779, 2012). "In the present study, we found that the intranasal administration of BMP9 significantly reduced the amyloid plaque load and Aβ levels in the brains of APP/PS1 mice, probably by promoting the efflux of Aβ mediated by LRP1." (PMID 28228716, 2017). "When LRP1 is deleted in neurons in adult mice, the half-life of interstitial fluid (ISF) Aβ in cortex increases, resulting in exacerbated amyloid pathology." (PMID 24904407, 2014). "Third, we identified two molecular mechanisms by which STAT3 inhibition may directly impact parenchymal and vascular amyloid pathogenesis—reduction in BACE1 activity and restoration of brain levels of LRP-1." (PMID 34911575, 2021). "A similar study, however, showed that lowering LRP1 levels in hippocampal neurons did not significantly alter Aβ levels and amyloid plaque numbers." (PMID 26464978, 2015). "Neuronal LRP-1, in contrast, remained unchanged after treatment, compatible with neuronal LRP-1 expression being independent of amyloidosis in AD mice." (PMID 23642031, 2013). "By power calculation, we should have been powered to observe a 30% decrease in amyloid plaque numbers and thus we conclude that reducing LRP1 levels does not produce a proportional decrease in amyloid plaque numbers." (PMID 22537779, 2012). "We compared amyloid plaque numbers in APPswe/PS1dE9 mice lacking LRP1 expression in hippocampus (n = 13) to mice with normal levels of LRP1 (n = 12)." (PMID 22537779, 2012). "However, at minimum, our study indicates that reducing the levels of LRP1 does not produce proportional reductions in amyloid plaque numbers in the hippocampus of the APPswe/PS1dE9 model." (PMID 22537779, 2012). "However, whereas LRP1 along brain capillaries showed amyloid clearance capacity, LRP1 expressed in neurons is not likely responsible for the removal of Aβ but may instead promote neuronal uptake of Aβ via its endocytic function." (PMID 23762130, 2013).
diabetes (22 papers, 2011 to 2025). "In addition, even in streptozotocin-induced diabetes, another pathology associated with neuroinflammation, a decrease in LRP1 expression at the level of the BBB was observed." (PMID 36142143, 2022). "After in vitro confirmation that mTORC1/SREBP1/LRP1 regulates the Aβ efflux mechanism, we constructed a diabetes model and further verified these effects in vivo." (PMID 36890627, 2023). "Based on these results, it can be concluded that diabetes induced mTORC1 activation, upregulated the expression of SREBP1, caused its translocation, and then downregulated LRP1." (PMID 36890627, 2023). "This information prompted us to identify the specific mechanism by which LRP1‐mediated Aβ efflux is regulated in diabetes." (PMID 36890627, 2023). "Many other alterations in BBB function occur with diabetes, including changes in the brain-to-blood (efflux) transporters P-glycoprotein (P-gp) and LDL receptor-related protein 1 (LRP-1)." (PMID 34829566, 2021). "When OCN is depleted, the protective effects of endothelial LRP1 depletion in diabetes are abrogated." (PMID 34489478, 2021). "This review briefly summarizes the growing body of literature on LRP1, its role in lipoprotein and glucose metabolism, and its potential influence on the metabolic syndrome and diabetes." (PMID 28584820, 2017). "This review summarizes the role of tissue-specific LRP1 in insulin signaling and its potential role as a link between lipoprotein and glucose metabolism in diabetes." (PMID 28584820, 2017). "In a recent study with patients diagnosed with AD and diabetes mellitus type-1, high levels of soluble LRP1 in CSF were described compared with the control subjects." (PMID 25926771, 2015). "LRP1 potentially plays a crossroad role between diabetes and cardiovascular disease." (PMID 32455133, 2020). "Although previous reports have evaluated the effect of pioglitazone on LRP1 expression in the brain using animal models, those mouse models had metabolic features of diabetes; thus, it was difficult to exclude the anti-diabetic effect of pioglitazone from the results." (PMID 30867485, 2019). "In addition, LRP1 levels decrease with age and AD and are closely related to Aβ deposition in the brain, suggesting that maintaining or increasing LRP1 levels during diabetes may be a potential strategy for treating and preventing diabetic cognitive dysfunction." (PMID 36890627, 2023). "We first included the following variables in the model: age, sex, education level, smoking and drinking history, diabetes duration, insulin use, BMI, HbA1c, FBG, PBG, HDL-C, LDL-C, TC, TG, ApoA1, ApoB, sLPR1, and the LRP1 genotype." (PMID 33013281, 2020). "Based on this evidence and on the role of LRP1 in cargo transport by endocytosis, there is no doubt that LRP1 dysregulation will affect important cell processes, and could be associated with disease states including diabetes, considering its effects on insulin and glucose metabolism." (PMID 29201005, 2017).